GRHL2 (grainyhead like transcription factor 2)
Diseases named in the same sentence as GRHL2 in open-access papers (continued):
Sharing a sentence is not in itself a finding about the gene and the disease.
cancer (continued). "Thus, our observations of GRHL2 impacting the cell cycle, together with GRHL2’s known role in mitosis, suggest that aberrant GRHL2 expression has the potential to contribute to cancer cell aneuploidy." (PMID 37761927, 2023). "TGFBR3, SnoN, and GRHL2 have also been shown to play dual roles in different types of cancer." (PMID 35765957, 2022). "However, more reports have shown that GRHL2 can inhibit epithelial-mesenchymal transition to inhibit cell migration and cancer metastasis." (PMID 35090432, 2022). "Expression of GRHL2 is increased in many cancers and the same applies to S100A10." (PMID 34356598, 2021). "Therefore, we investigated the expression of GRHL2 target genes that have roles in cancer progression." (PMID 34771571, 2021). "Additionally, we focus on human GRHL2 as an important determinant of the epithelial phenotype during development and as a gatekeeper of epithelial differentiation in several human cancers." (PMID 32974388, 2020). "We performed pancreatosphere formation assay to investigate whether GRHL2 confers the property of putative cancer stem cell (CSC) in CFPAC‐1 cells." (PMID 28960866, 2017). "Thus, the functional roles and clinical impact of GRHL2 vary with cancer type, and its expression and effect in pancreatic carcinogenesis has not yet been investigated." (PMID 28960866, 2017). "However, one factor (GRHL2) was identified in the top 1 % of all correlations for 31 different motifs spread among five of the 10 different cancer types studied." (PMID 25994056, 2015). "In this study, the controversial expression of Mki67 between Grhl2 overexpressed cancer cell lines and Grhl2 overexpressed breast epithelia cell line might be due to the difference in cell cultures or cell context-specific effects." (PMID 23441166, 2013). "Interestingly, these TFs, together with OVOL1/2 (Ovo Like Transcriptional Repressors 1 and 2), had previously been suspected to inhibit epithelial–mesenchymal transition in cancer cells with a hierarchically dominant position for GRHL2, which directly induces expression of EHF and OVOL2." (PMID 41385584, 2025). "However, the role of GRHL2 in oncogenesis varies in different cancer types." (PMID 37761927, 2023). "Indeed, GRHL2 inhibits the epithelial-to-mesenchymal transition (EMT) in some cancer cells." (PMID 37761927, 2023). "Together, this suggests that GRHL2 function may vary depending on the cancer cell context." (PMID 36768838, 2023). "Therefore, the relatively high levels of CDH3, OVOL2, and GRHL2 in patients with poor survival might highlight the role of hybrid E/M phenotype in metastatic progression, at least in these carcinomas." (PMID 27008704, 2016). "Bicluster 1 CpGs were found enriched in binding regions of TFs including GRHL2, TFAP2C, FOXA1, ER, CEBPB and NR5A2, TFs known to be important in many cancer‐related functions such as proliferation, stemness and epithelial‐to‐mesenchymal transition (EMT)." (PMID 38671580, 2024). "A recent study showed that GRHL2 is a key player in EMP and other studies indicated that GRHL2 directly regulates EpCAM and RAB25 expression, which are correlated with cancer progression." (PMID 34771571, 2021). "GRHL2 upregulates expression of the MIR141, MIR200A, MIR200B, MIR200C and MIR429 microRNAs by binding to their regulatory elements in a number of cancers." (PMID 32005677, 2020). "GRHL2 suppresses EMT and has an expression pattern inversely correlated with that of ZEB1 in numerous cancers." (PMID 32005677, 2020). "Herein, we explored and defined novel functional roles for GRHL2 in the regulation of EMT and MET during cancer progression in PDAC cells." (PMID 28960866, 2017). "A similar effect on inhibited proliferation was also observed for knockdown of GRHL2—another proposed PSF—in lung and ovarian cancer cells." (PMID 29187638, 2017). "Within this 8q22.3 gene cluster, GRHL2 and UBR5 have been shown, through their respective proteins, to suppress death receptor-induced apoptosis in cancer cells." (PMID 26887977, 2016).
cancer (continued). "Among genes that are not listed as cancer genes in “Cancer gene census” it is worth mentioning GRHL2 and SMURF2." (PMID 39208653, 2024). "GRHL2 may prevent a complete EMT and maintain cancer cells in a hybrid EMT state that is believed to be crucial for cancer cell plasticity, which supports invasion and metastasis." (PMID 36691073, 2023). "The most significantly enriched TF gene was GRHL2, known as an EMT suppressor in various cancers." (PMID 34356119, 2021). "Taking into account the increased level of S100A10 and GRHL2 in many cancers, it is possible that regulation of S100A10 expression by GRHL2 might have an impact on cancer progression and metastasis." (PMID 34356598, 2021). "Moreover, nonsense mutations were detected in GRHL2, GRIN1, NOL9 and TTC21B, however only GRHL2 and GRIN1 were previously shown to be involved in cancer." (PMID 29854292, 2018). "In addition, OVOL1/2 is highly correlated with GRHL2 and CDH3 (positively) and with ZEB1 (negatively) in a panel of 877 cell lines from The Cancer Cell Line Encyclopedia (CCLE)." (PMID 27008704, 2016). "Associations between GRHL2 expression and clinical outcome in different cancer types reported so far mostly, but not exclusively, are based on differences in GRHL2 expression determined using publicly available omics datasets and, not surprisingly, in many cases even yielded contradictory results." (PMID 40889682, 2025). "Accordingly, pathway analyses predicted an enrichment of cancer-associated processes linked to cellular proliferation and metastasis, and several transcription factors were predicted to be associated with TOC and ESCC, including negative enrichment of GRHL2." (PMID 39131151, 2024). "However, within a cancer type such as EOC, the expression of GRHL2 was heterogeneous." (PMID 26887977, 2016). "Interestingly, although the median GRHL2 expression displayed a bimodal-like distribution, with an almost equally low GRHL2 expression in cancers with high EMT scores, we observed a continuous increase of EMT scores in cancers with low GRHL2 expression." (PMID 26887977, 2016). "We used the 4T1 model to answer this question, in which disseminated cancer cells had undergone EMT and did not express Grhl2." (PMID 23284647, 2012). "Besides that, some affected new potential cancer drivers (genes that were not cataloged at CGC) were identified, such as CACNA1E, GRHL2, MTHFD2, PIK3AP1, RSBN1, SEMA6D, and SMURF2." (PMID 39208653, 2024). "No connections of these clusters with GRHL2 were visible but the interaction of GRHL2 with CLDN4 was shown as well as co-expression of GRHL2 with TACSTD2, a transmembrane receptor regulating cell proliferation and migration in development and cancer." (PMID 36691073, 2023).
GRHL2 also shares sentences with these, for which no sentence is quoted: Hearing impairment (2 papers); sensorineural hearing loss (2); acromegaly (1); acute leukemia (1); adenocarcinoma (1); alcoholic liver diseases (1); anemia (1); asthma (1); atherosclerosis (1); Breast Invasive Carcinoma (1); chronic hepatitis B (1); cleft lip (1); Cohen syndrome (1); congenital stromal corneal dystrophy (1); corneal edema (1); cutaneous squamous cell carcinoma (1); distal renal tubular acidosis (1); dwarfism (1); EEC syndrome (1); Esophageal Neoplasms (1); esophageal squamous cell carcinoma (1); fleck corneal dystrophy (1); gelatinous drop-like corneal dystrophy (1); genetic disorder (1); glioblastoma (1); glioma (1); Gynecological tumor (1); head and neck squamous cell carcinoma (1); infection (1); Liver abscess (1).
A further 26 diseases each share a sentence with GRHL2 in 1 paper.